CRP (C-reactive protein)
Diseases named in the same sentence as CRP in open-access papers (continued):
Sharing a sentence is not in itself a finding about the gene and the disease.
co-infection (continued). "Therefore, both traditional bacterial culture and NGS analysis revealed a low rate of bacterial co-infection in children with RMPP, indicating that CRP increase in RMPP might mainly result from inflammation." (PMID 30416990, 2018). "We investigated markers of immune activation (neopterin) and inflammation (CRP) in TB patients with and without HIV coinfection and their association with CD4 cell levels, and determined their predictive capacity as alternative markers of advanced immunosuppression." (PMID 26630153, 2015). "Using single liver-synthesized biomarkers (e.g. C-reactive protein) to represent inflammation may not be appropriate in HIV/HCV co-infection." (PMID 23987993, 2013). "In the viral-bacterial co-infection group, although bacteria were detected, some of the bacteria might have been colonizing rather than serving as primary pathogens, as colonizing bacteria typically do not significantly induce elevated CRP levels in the host." (PMID 40046054, 2025). "All investigated inflammatory markers, CRP, WBC, procalcitonin and NLR, were elevated in patients with a detected bacterial co-infection as compared to patients without a bacterial co-infection." (PMID 35100984, 2022). "Of 6 cases with clinical characteristics consistent with possible bacterial pneumonia (CRP ≥40 mg/ L, alveolar consolidation, and no RSV co-infection), 4 were colonized with pneumococcus but the median density was low (7.2 x 103 copies/mL)." (PMID 32348330, 2020). "Therefore, elevated WBC and CRP in RMPP patients might not be indicators of bacterial co-infection." (PMID 30416990, 2018). "Serum MCP-1 and CRP concentrations were significantly increased in HIV-infected patients irrespective to antiretroviral treatment, while co-infection did not result in further differences." (PMID 20707918, 2010). "The top three markers contributing most to overall network density by AUC in the subgroup of those without HIV-1 co-infection were CXCL10, C-reactive protein, and IFNα2, whereas the top three markers in the subgroup of those with HIV-1 co-infection were IL-17A, IL-1β, and TNFα." (PMID 34386782, 2021).
myocarditis (145 papers, 2010 to 2026). Myocarditis is a condition that is characterized by inflammation of the heart muscle (myocardium). "Raised CRP and leucocyte counts are also associated with dengue myocarditis, and the results are highly significant compared to non-myocarditis cases (p < 0.001)." (PMID 40535371, 2025). "The IL-1 pathway is associated with high-CRP responses and has been claimed to play a shared pivotal role across different forms of myocarditis, including lupus myocarditis." (PMID 39047157, 2025). "Although CRP was reported to be a potential biomarker to detect inflammation which is correlated as an important symptom of myocarditis, no investigation has been done to date to identify the association of CRP with myocarditis." (PMID 39564010, 2024). "We found a strong association between the enhanced levels of CRP and myocarditis as compared to healthy control patients." (PMID 39564010, 2024). "The present systematic review and meta-analysis were performed to get insight into the association between the presence and magnitude of CRP in patients suffering from myocarditis as compared to the control participants." (PMID 39564010, 2024). "Due to its strong association with myocarditis, CRP levels are tested as a routine histological diagnosis assay and are widely used for earlier detection and monitoring of myocarditis." (PMID 39564010, 2024). "For those carrying the DSP variant, all laboratory tests, including TnI and CRP, were performed in a stable phase as part of this study, and for patients with myocarditis, the test were conducted during the period of hospitalization." (PMID 37008330, 2023). "Regarding cardiac pathology, we found an association between myocarditis and a two-fold rising of troponin (P = 0.010) and CRP over 80 mg/dL (P = 0.008)." (PMID 38301088, 2023). "The history of recent infections (82.5% vs. 6%) and C-reactive protein (CRP) levels on admission (Me 45.9 vs. 3.4) was more associated with myocarditis." (PMID 35207189, 2022). "In spite of the still debated diagnostic role in myocarditis, CRP is elevated in the majority of patients with acute pericarditis where it is used to monitor disease activity and to establish the appropriate length of anti-inflammatory treatment." (PMID 36498643, 2022). "Routine measurement of NT-proBNP and CRP are preferred over troponin for risk stratification in the cases of hemodynamically stable myocarditis." (PMID 35566598, 2022). "It should be known that SARS-CoV-2-associated myocarditis has higher C-reactive protein and pro-B-type N-terminal natriuretic peptide (NT-proBNP) levels in comparison with myocarditis with other etiologies." (PMID 36611412, 2022). "In the early risk period of clozapine-induced myocarditis, monitoring results using inflammatory markers, such as C-reactive protein, and cardiac damage indicators troponin and brain natriuretic peptide are inconsistent." (PMID 35873271, 2022). "We assessed the diagnostic and prognostic correlates of C-reactive protein (CRP) at diagnosis in patients with myocarditis." (PMID 36498643, 2022). "In conclusion, routine measurement of NT-proBNP and CRP are preferred over troponin for risk stratification in hemodynamically stable myocarditis." (PMID 35566598, 2022). "Similar to other inflammatory diseases, acute myocarditis is associated with increased levels of CRP during the acute phase." (PMID 35566598, 2022). "Both elevated troponin and CRP were found to be good diagnostic measures for myocarditis with a ROC AUC of 0.975 and 0.896, respectively." (PMID 35048875, 2021). "Therefore, CRP needs to be considered as a potential diagnostic and prognostic biomarker for myocarditis." (PMID 39564010, 2024). "Therefore, this systematic review and meta-analysis aims to determine the association between the presence of CRP and myocarditis." (PMID 39564010, 2024). "Participants with the DSP variant had lower TnI and CRP levels than those with myocarditis." (PMID 37008330, 2023).
myocarditis (continued). "Clinical and diagnostic role of C-reactive protein in myocarditis patients." (PMID 36498643, 2022). "In light of the TFR1 level has been demonstrated significantly increased in acute myocarditis patients and associated with augmented inflammation (CRP, IL-6), we hypothesized that TFRC might be a key effector gene of pro-ferroptosis in CVB3 infection." (PMID 35821227, 2022). "In multivariate logistic regression analyses after adjustment for CVRF, elevated TnI values (≥ 136.5 pg/ml) (OR 3.011 [95%CI 1.215–7.464]; p = 0.017) as well as elevated CRP values (≥ 8.15 mg/l) (OR 1.985 [95%CI 1.160–3.397], p = 0.012) were independently associated with myocardial inflammation." (PMID 33542341, 2021). "Additionally, but to a smaller extent, the combination of TnI and CRP was also independently associated with myocardial inflammation (OR 5.761 [95% 1.240–26.771], p = 0.025)." (PMID 33542341, 2021). "During myocarditis, the cardiac cells lying in the middle layer of the cardiac wall get damaged which eventually leads to the release of inflammatory cytokines resulting in the upregulation of CRP synthesis and heightened immune responses against the causative agents." (PMID 39564010, 2024). "As in other forms of myocarditis, laboratory findings can include elevated troponin, brain natriuretic peptide, and inflammatory markers such as erythrocyte sedimentation rate and C-reactive protein." (PMID 39847306, 2025). "The marked increase in CRP and procalcitonin levels reflected both infection driven inflammatory response and ongoing myocardial inflammation." (PMID 41375765, 2025). "Scientists propounded a conclusion that this group of patients frequently suffer from prolonged systemic inflammation with increased CRP and troponins as well as subclinical myocarditis and impairment of left ventricle function." (PMID 41462903, 2025). "Elevated C-reactive protein levels (>100 mg/L) and troponin values ≥2 times the upper normal limit provide 100% sensitivity for identifying myocarditis in symptomatic individuals." (PMID 40741548, 2025). "C-reactive protein (CRP) was also significantly raised in the myocarditis group (5.5 ± 5.3 mg/dL vs 2.3 ± 2.1 mg/dL, p < 0.001)." (PMID 40535371, 2025). "In contrast, a multivariable logistic regression model incorporating age, BMI, CRP, and significant ST-segment elevation showed a substantially improved discriminative ability for predicting (peri-) myocarditis (AUC = 0.8173)." (PMID 41341294, 2025). "Although myocarditis was deemed unlikely based on normal C-reactive protein levels, definitive exclusion of alternative etiologies requires cardiac magnetic resonance imaging, which remains pending." (PMID 40861622, 2025). "Univariate ROC curve analyses of age, BMI, CK at admission, CRP, and significant ST-segment elevation demonstrated individually modest predictive value for (peri-) myocarditis." (PMID 41341294, 2025). "CRP levels were also lower in cardiomyopathy patients compared to myocarditis and AMI/IHD groups, with both differences reaching statistical significance (p < 0.05)." (PMID 40141814, 2025). "Mean (±standard deviation) leucocyte count 9.1 (±4.7) ×109/L, alanine aminotransferase (ALT) 604 (±937) IU/L, aspartate aminotransferase (AST) 2076 (±4202) IU/L, and C-reactive protein (CRP) 5.5 (±5.3) mg/dL were significantly higher in the myocarditis group." (PMID 40535371, 2025). "Based on previously published data NLR correlates with LVEF in pediatric patients with acute myocarditis and is a better predictor than biomarkers such as CRP, PCT, high-sensitivity troponin, BNP and NT-proBNP." (PMID 41597048, 2025). "Patients with (peri-) myocarditis were significantly younger, had lower BMI, higher CK and CRP levels, and more frequent ST-segment elevations." (PMID 41341294, 2025). "Patients exhibited varying levels of hs-Troponin I, NT-proBNP, and CRP, with significant differences observed between those with cardiomyopathy, myocarditis, AMI/IHD, and normal CMR scans." (PMID 40141814, 2025).
myocarditis (continued). "One patient (7.7%) with myocarditis and signs and symptoms of inflammation (high CRP and fever), already on steroids, MMF and anakinra, died of sudden cardiac death upon anakinra suspension." (PMID 37796832, 2024). "Patients with ASS with myocarditis frequently presented with fever and increased CRP, suggesting the existence of an inflammatory phenotype." (PMID 37796832, 2024). "Actually, both pericarditis and myocarditis can start with sudden onset precordial pain and concomitant CRP and troponin elevations, along with overlapping ECG changes; additionally, both pericarditis and myocarditis can be caused by a cardiotropic virus." (PMID 39598049, 2024). "The main forest plot using the random effect model detected the value of the mean difference (MD) as 6.03 (95%CI: 10.01-11.21) which indicated that the CRP was higher in myocarditis patients as compared to healthy control patients." (PMID 39564010, 2024). "The MD (6.03 (95%CI: 2.41-9.64), p<0.00001) corresponds to a higher and significant CRP level in myocarditis as compared to the control group." (PMID 39564010, 2024). "Higher TnI levels in myocarditis cases were associated with lower LV strain and lower LVEF, higher CRP levels also correlated with lower LVEF." (PMID 39452564, 2024). "The patient was found to have electrocardiogram features and symptoms in keeping with pericarditis, C-reactive protein elevation, and a peak high-sensitivity troponin level of 9,992 ng/L suggestive of a component of myocarditis." (PMID 38736762, 2024). "After the search was completed, the authors rigorously searched for research articles that had data regarding CRP levels in patients with myocarditis which was compared with healthy controlled patients." (PMID 39564010, 2024). "Higher TnI levels in cases of myocarditis were associated with lower LV strain and lower LVEF; higher CRP levels also correlated with lower LVEF." (PMID 39452564, 2024). "Our findings strongly suggest that CRP can be a strong biomarker for the diagnosis and prognosis of myocarditis especially when merged with the other conventional methods." (PMID 39564010, 2024). "Seventy-eight percent of cases had C-reactive protein (CRP) levels exceeding 100 mg/dL, and 45% of patients had cardiac involvement (myocarditis or transient coronary involvement)." (PMID 39119587, 2024). "This meta-analysis used the mean value and standard deviation (SD) of the CRP within the study participants along with the total number of participants of two comparative groups including myocarditis patients and healthy control groups, respectively." (PMID 39564010, 2024). "We identified the mean difference (MD) in CRP levels between the myocarditis patients and healthy controls." (PMID 39564010, 2024). "Median peak troponin level was 8466 pg/ml (1458–26,825) and median maximum C reactive protein (CRP) was 35.3 mg/l (10.0–86.0) in patients with acute myocarditis." (PMID 36961599, 2023). "Here, we investigated a cohort of patients who developed myocarditis and/or pericarditis with elevated troponin, B-type natriuretic peptide, and C-reactive protein levels as well as cardiac imaging abnormalities shortly after SARS-CoV-2 mRNA vaccination." (PMID 37146127, 2023). "Laboratory values for CRP and TnI were available from almost all participants with the DSP variant (21/29 and 28/29, respectively) and from all 15 patients with myocarditis." (PMID 37008330, 2023). "In univariate analysis using Fischer’s exact test, myocarditis had significant relationships with C-reactive protein (CRP) levels higher than 80 mg/dL (P=0.008) and elevated cardiac troponin levels higher than two-fold (P=0.01)." (PMID 38301088, 2023). "We enrolled 59 patients (80% males, mean age 29 years) with CMR-derived mild myocarditis (hs-Troponin-T 552 ng/L, CRP 28 mg/L; LVEF 57 ± 7%, LGE 3 segments)." (PMID 37416926, 2023).
myocarditis (continued). "Except for some notably increased serum CRP titers in myocarditis, there exist reports with lower CRP (0.7 mg/L in a SARS-CoV-2 case)!" (PMID 37873776, 2023). "In these patients, after achieving control of the disease with normalization of CRP, ferritin, and signs of myocarditis, anakinra was reduced by one dose every 3 days until discontinuation." (PMID 37238314, 2023). "Myocarditis is usually found in patients with high C-reactive protein, serum lactate, and troponin T, but these markers have a low negative predictive value to rule out patients with other diseases suspected to be myocarditis." (PMID 36420287, 2022). "In patients with suspected acute myocarditis, the level of NT-proBNP and CRP were positively correlated with the severity of the disease, while troponin was not." (PMID 35566598, 2022). "Methods and results: We retrospectively enrolled patients with clinically suspected (CS) or biopsy-proven (BP) myocarditis, with available CRP at diagnosis." (PMID 36498643, 2022). "Conversely, we found lower CRP levels among patients with biopsy-proven myocarditis, arrhythmic presentation, more advanced NYHA class at presentation and a higher likelihood of AHA positivity." (PMID 36498643, 2022). "Raised CRP identifies myocarditis patients with less severe clinical features, but shows negligible importance in predicting patients’ outcome." (PMID 36498643, 2022). "We aimed to assess CRP in patients with clinically suspected and biopsy-proven myocarditis and its clinical, laboratory and imaging correlates, and to explore its potential role as a prognostic biomarker." (PMID 36498643, 2022). "Other serum markers of inflammation, including white blood cell count, erythrocyte sedimentation rate, and C-reactive protein levels, can be elevated in acute myocardial inflammation, but show low accuracy for determining the presence of active myocarditis." (PMID 35159224, 2022). "The lower CRP values that we found in myocarditis patients with worse outcomes are in keeping with an established major role for adaptive response, i.e., autoimmunity, rather than innate immunity." (PMID 36498643, 2022). "It graphically presents that patients suffering from acute myocarditis are younger, with abnormal levels of CRP values and past histories of recent infections, in contrast to patients with AMI." (PMID 35207189, 2022). "As expected, patients with acute myocarditis had significantly higher inflammation markers (C-reactive protein) and white blood cell counts than the control group, as well as significantly higher levels of troponin I and brain natriuretic peptide (BNP)." (PMID 33804042, 2021). "CRP >10 mg/dl for example, strongly suggested the presence of myocarditis in a pooled cohort of 556 patients regarded having MINOCA." (PMID 34032303, 2021). "After adjusted by age, fever duration before initial IVIG, WBC, CRP, ALT, ALB, TBil, Na+, SII was identified as an independent risk factor for myocarditis (p = 0.012)." (PMID 34504878, 2021). "Patients with myocardial inflammation were more often smokers (52.4% vs. 39.8%, p = 0.013) and had higher C-reactive protein (CRP) levels (5.4 mg/dl vs. 3.7 mg/dl, p = 0.003)." (PMID 33542341, 2021). "Three measures (tachycardia, elevated CRP and raised troponin) had a 100% sensitivity for myocarditis, meaning that all instances with confirmed myocarditis showed these features." (PMID 35048875, 2021). "Median peak troponin level was 8310 pg/ml (min–max 1490–26,800) and median maximum C-reactive protein (CRP) was 36.4 mg/l (10.2–83.4) in patients with acute myocarditis." (PMID 34086089, 2021). "The first 4 weeks of starting CLZ treatment should incorporate weekly monitoring of inflammatory (C-reactive protein; CRP) and myocardial damage (troponin I or T) markers in routine blood work for signs of myocarditis." (PMID 29670504, 2018).